NPY (neuropeptide Y)
Diseases named in the same sentence as NPY in open-access papers (continued):
Sharing a sentence is not in itself a finding about the gene and the disease.
infection (17 papers, 2010 to 2025). The state of being infected such as from the introduction of a foreign agent such as serum, vaccine, antigenic substance or organism. "Infection caused an imbalance between y7 and y8b and was alleviated by NPY." (PMID 41007974, 2025). "Additionally, whether the immune-protective effects of NPY on the gastrointestinal tract are applicable to different pathogenic infections requires further study." (PMID 41007974, 2025). "We found that infection increased the production of PYYb, and treatment with Neuropeptide Y further boosted this effect." (PMID 41007974, 2025). "NPY treatment alleviates the inflammatory response, reduces oxidative stress, and mitigates gastrointestinal tissue damage induced by infection." (PMID 41007974, 2025). "This activation was notably reversed by NPY co-treatment, suggesting a regulatory effect of NPY on infection-induced y7 expression." (PMID 41007974, 2025). "After accounting for other demographic and infection factors (age, sex, serology, NPY haplotype), prolonged illness at 6 months was positively associated with greater illness severity at baseline (p < 0.001) and RRV infection (p < 0.01)." (PMID 35959390, 2022). "Primary porcine microglial cells decrease their expression of NPY when treated with TLR2 agonists, indicating that microglial cells are involved in the altered expression of NPY after SE infection." (PMID 31803186, 2019). "The majority of the neuropeptides in the CNS were significantly less abundant at 12 days post-infection, such as Pep 1, Pep 2, NPY, PTSP-like, Pep 4, AAP12 and pleurin." (PMID 28578678, 2017). "Notably, co-treatment with NPY markedly suppressed the infection-induced upregulation of pyyb, particularly in the midgut at 3 h and 6 h." (PMID 41007974, 2025). "These infection-induced changes were further modulated by exogenous NPY administration, which exerted protective effects by suppressing inflammatory responses, maintaining tissue architecture, and restoring immune and oxidative homeostasis at the systemic level." (PMID 41007974, 2025). "In rodent models, infection has been reported to lead to structural changes and mild apoptosis in neurons, as well as increases in neuropathic damage markers including Nav1.3, neuropeptide Y (NPY), and galanin." (PMID 39958365, 2025). "Our findings suggest that Neuropeptide Y could be developed as a treatment to improve disease resistance and gut health in farmed fish, offering a promising approach to controlling infections and improving the sustainability of aquaculture." (PMID 41007974, 2025). "In this study, we examined how Neuropeptide Y and related molecules, including a similar peptide called PYYb and two specific receptors, respond to infection and whether they help the fish fight disease." (PMID 41007974, 2025). "On the other hand, circulating NPY may also have contributed to the NPY levels in the CSF, especially in the light of the elevated blood–CSF permeability post-SE infection." (PMID 31803186, 2019). "In addition, combined deletion of NPY and PYY aggravates and prolongs the weight loss caused by Bacille Calmette–Guérin, which attests to an important role of NPY and PYY in orchestrating homeostatic reactions to infection and immune stimulation." (PMID 29213271, 2017). "The identification of specific neuropeptides, such as PNOC and NPY, as potential interactors with the HIV entry machinery opens new avenues for investigating their role in infection and pathogenesis." (PMID 41303692, 2025). "Neuroinflammation-related neuropeptide Y (NPY), IL-18, and MMP-14 showed distinct changes in the CSF and several brain regions (the prefrontal cortex, PVWM, and hippocampus) 24 h after infection." (PMID 31803186, 2019). "The findings attest to an important role of NPY and PYY in orchestrating homeostatic reactions to infection and immune stimulation." (PMID 23992467, 2013).
infection (continued). "Our findings are in agreement with these observations, but substantially advance those by showing that in addition to PV and SST inhibitory cells, GABAergic neurons expressing nNOS, NPY, and CCK can be also a subject of infection by CaMKIIα promoter-controlled constructs." (PMID 36963833, 2023). "Among these proteins, neuropeptide Y (NPY), a neuropeptide in the CNS with pleiotropic roles in neurogenesis, neuroprotection, and neuroinflammation, showed decreased abundance in the CSF after SE infection." (PMID 31803186, 2019). "Substance P, NPY, and CGRP may induce chemotaxis of neutrophils, monocytes and macrophages, therefore attract phagocytic cells to the site of infection." (PMID 22551165, 2012). "Although it must not be neglected that developmental compensations may mask the full implication of PYY and NPY, our results attest to an important physiological role of NPY and PYY in orchestrating multiple homeostatic reactions in the face of infection and immune stimulation." (PMID 23992467, 2013). "Together, these results are consistent with the notion that the Tir NPY signalling pathway is not essential for the formation of A/E lesions and for the establishment of colonization, but promotes bacterial expansion from the initial infection sites." (PMID 19889090, 2010). "NPY was exclusively identified in non-infected CNS, while NKY supported by three MS peptides (GDKDDLYSAILQAAESPS, TYATTDATLETILNVLKSHAQSLRQLESTVYEQ and TYATTDATLETILNVLKSHAQSLRQLESTVYEQa) was only detected at pre-patent infection stage." (PMID 28578678, 2017).
neurological diseases (7 papers, 2014 to 2024). "A study in the United States showed that the increased number of monocytes infiltrated into the brain of NPY-deficient mice can aggravate the process of neurological diseases." (PMID 34422139, 2021). "Several studies have shown that NPY is a key neurological biomarker demonstrating NPY mRNA expression, and NPY binding sites are affected in different ways for each neurological disease." (PMID 35566093, 2022). "Based on protective effects of NPY in neuronal networks, NPY signaling is increasingly considered a novel therapeutic target for neurodegenerative and neurological disorders (see review)." (PMID 34439588, 2021). "NPY has been shown to be involved in the regulation of a variety of neurological diseases." (PMID 34422139, 2021). "NPY is related to neurological diseases and exerts neuroprotective functions." (PMID 33546356, 2021). "Although the pro-neurogenic role of exogenous NPY has been extensively evaluated in both in vitro and in vivo experimental models of neurologic disorders, evidence that the newly-generated cells survive and become functionally integrated neurons has been poorly pursued." (PMID 24516629, 2014).
brain diseases (4 papers, 2017 to 2023). "More recently, it has also been implied in several brain disorders since its other substrates include neuropeptide Y, secretin, substance PACAP and amyloid peptides." (PMID 36826039, 2023). "While previous work demonstrates the potential of NPY-based pharmacotherapies for treating psychiatric illnesses, further work is needed to understand the functional effects of NPY signaling and its implications for brain diseases." (PMID 35800635, 2022). "Above review of NPY illustrates its important role in physiology as well as pathophysiology of several brain disorders with dysregulated emotionality and points to its potential as a therapeutic agent that can be administered intranasally." (PMID 28824541, 2017). "NPY has gained a lot of interest from the scientific community over the years and has been broadly studied and biologically and pharmacologically characterized due to its involvement in the pathophysiology of several diseases, especially brain diseases." (PMID 35744852, 2022).
inflammation (4 papers, 2013 to 2024). Aberrant reaction of the microcirculation characterized by movement of fluid and leukocytes from the blood into extravascular tissues. "Along with airway inflammation, allergen challenges (day 18) significantly increased the release of NPY in BALF and serum." (PMID 39345572, 2024). "For instance, orthologs for CRH and urocortins, Substance P, NPY, alpha-MSH, ghrelin and GIP have been described in zebrafish and in parallel implicated in the pathogenesis of intestinal inflammation, in mouse and human studies." (PMID 24376661, 2013).
heart disease (3 papers, 2016 to 2025). "An understanding of the role of co‐transmitters such as NPY may ultimately lead to novel therapeutic targets and biomarkers to improve risk stratification and prognostication in patients with cardiac disease." (PMID 38847435, 2025). "Other peptides like Neuropeptide Y (NPY) and Substance P (SP) colocalize with NE or are associated with its function and were found to be relevant to heart disease." (PMID 27242392, 2016). "Neuropeptide Y (NPY) is the most abundant neuropeptide in the heart and a co-transmitter of the sympathetic nervous system that plays a role in cardiac diseases." (PMID 31811615, 2020). "Despite these intriguing hints, to our knowledge the mutual effects of chemokines, Substance P, NPY, NGF, and ANS in the progression of heart disease remain largely unknown." (PMID 27242392, 2016). "NPY may have proinflammatory effects in atherosclerosis, but the inflammatory effects have not been studied in the context of heart diseases." (PMID 31811615, 2020).
bacterial infection (2 papers, 2023 to 2025). "In teleost, Neuropeptide Y (NPY) is identified to be involved in the immune regulation of intestinal tissues during bacterial infections." (PMID 41007974, 2025). "The observed upregulation of il-10 further indicated that NPY could facilitate the resolution phase of inflammation, contributing to immune homeostasis during bacterial infection." (PMID 41007974, 2025). "Therefore, the aim of our study was to estimate the impact of the severity of the disease and the type of bacterial infection in CF patients on the serum level of appetite-regulating hormones including leptin, ghrelin, NPY, ASP, POMC, KISS, PYY, and α-MSH." (PMID 37111072, 2023). "In addition, we found that neither the severity of the disease nor the type of bacterial infection affects the level of other tested hormones that regulate appetite (ghrelin, NPY, ASP, POMC, KISS, PYY, and α-MSH)." (PMID 37111072, 2023).
central nervous system disorder (2 papers, 2019 to 2024). A disease involving the central nervous system. "In conclusion, the NPY-Nanoluc is a sensitive reporter of DCV exocytosis in mammalian neurons, suitable for pharmacological and genomic screening for DCV exocytosis genes and for mechanism-based treatments for central nervous system disorders." (PMID 38677517, 2024).
gastrointestinal disorders (2 papers, 2015 to 2025). "In recent years, the pathological mechanisms of several gastrointestinal disorders have been elucidated from the viewpoint of gastrointestinal peptides such as ghrelin, leptin, substance P, motilin, and neuropeptide Y (NPY)." (PMID 40045433, 2025).
NPY also shares sentences with these, for which no sentence is quoted: alcoholism (7 papers); acute myocardial infarction (5); absence seizures (4); Hepatic steatosis (4); Hypercholesterolemia (4); diabetic retinopathy (3); endometritis (3); Infertility (3); panic disorder (3); Alcohol Addiction (2); binge eating (2); breast (2); chronic fatigue syndrome (2); chronic periodontitis (2); CNS tumors (2); dependence (2); drug dependence (2); end stage renal disease (2); hypertriglyceridemia (2); hypogonadotropic hypogonadism (2); ischemic cardiomyopathy (2); kidney failure (2); left ventricular hypertrophy (2); Machado-Joseph disease (2); obsessive-compulsive disorder (2); Pain (2); Parkinson’s (2); pelvic organ prolapse (2); periodontal disease (2); peripheral neuropathy (2).
A further 104 diseases each share a sentence with NPY in 2 papers or fewer.